IL10 (interleukin 10)
Diseases named in the same sentence as IL10 in open-access papers (continued):
Sharing a sentence is not in itself a finding about the gene and the disease.
tumor (continued). "In an in vivo intervention model, pks+ E. coli accelerates tumorigenesis in IL-10−/− and APCMin/+ mice and increases tumor burden in transplanted tumor models." (PMID 40941154, 2025). "In our co‐culture system, interleukin 4 (IL4), IL8, and IL10 levels were significantly increased in the medium from THP‐1 macrophages co‐cultured with tumor cells overexpressing ITGβ8, which indicates that more macrophages exhibited the M2 phenotype." (PMID 39535362, 2025). "Within the tumor microenvironment, MDSCs exert immunosuppressive effects by releasing nitric oxide (NO), IL-10, and TGF-β." (PMID 40948940, 2025). "Concurrently, IL‐10 activates exhausted CD8+ T cells (tumor‐resident memory‐like, CD62L−CD69+), boosting IFN‐γ production and cytotoxicity, which contributes to tumor elimination, recurrence prevention, and metastasis inhibition." (PMID 40878391, 2025). "They suppress the activity of effector T cells and natural killer (NK) cells by secreting inhibitory cytokines such as TGF-β and IL-10, weakening the body’s immune response to the tumor." (PMID 40094019, 2025). "The ingestion of apoptotic cells by macrophages and other phagocytes can lead to the release of anti-inflammatory cytokines, such as TGF-β and IL-10, which suppress effective anti-tumor immune responses and promote tumor growth and metastasis." (PMID 39995691, 2025). "Another possible pro-tumor pathway involves IL-4 and IL-10 secretion, which is connected with Vδ1 T cells exhibiting a regulatory phenotype and inhibiting Vδ2 T cell function." (PMID 40148988, 2025). "IL-10: All patients showed a marked reduction in IL-10 staining following treatment, indicating suppression of the immunosuppressive tumor milieu." (PMID 41459907, 2025). "MφU-SNFIB-MAA-CIT- stimulated HCAECs exhibited upregulation of tumor microenvironment pathways, IL-4 and IL-13 signaling, inflammation signaling, and fibrosis signaling, with concurrent downregulation of IL-10 signaling pathways." (PMID 41296447, 2025). "It is essential for local cancer immunotherapy that IL-10 has the capacity to stop an immune response from growing at the tumor site." (PMID 40933989, 2025). "Within the tumor microenvironment (TME), tumor-associated macrophages predominantly adopt an M2-like phenotype, secreting cytokines such as IL-10 and TGF-β, chemokines like CCL2 and CCL5, and proteases such as matrix metalloproteinases (MMPs)." (PMID 40487409, 2025). "The tumor environment is usually dominated by immunosuppressive cells and molecules, such as regulatory T-cells (Tregs), tumor-associated macrophages (TAMs), and cytokines such as TGF-β and IL-10, which inhibit the immune response generated by the vaccine." (PMID 40006583, 2025). "Upon being recruited to inflammatory tumor tissues in response to chemokines like CCL2, CCL5, CXCL8, and CXCL12, MDSCs rapidly produce immunosuppressive mediators, including ARG1, NO, TGF-β, and IL-10, which further impair anti-tumor immunity." (PMID 40563367, 2025). "By decreasing the activity of anti-tumor immune cells, anti-inflammatory cytokines such as IL10 and its expression level play a significant role in the equilibrium phase and cause the tumor to enter the escape phase." (PMID 41019045, 2025). "Together with reduced IL-10 elevation seen in the current study, they imply a better preservation of NK-cell function and anti-tumor immunity." (PMID 41155334, 2025). "The tumor can thwart the host immune system’s ability to eliminate it by using IL-10 production at the tumor location." (PMID 40933989, 2025). "They inhibit T-cell proliferation and cytotoxic T-cell activation while suppressing macrophage-mediated tumor-killing by producing cytokines such as IL-10 and TGFβ." (PMID 41208963, 2025). "Studies have shown that P. gingivalis induces an anti-tumor iNKT cell phenotype by increasing the expression of IL-17, GM-CSF, and IL-10, which reduces iNKT cell-mediated tumor cell cytotoxicity." (PMID 41473772, 2025).
tumor (continued). "Not all γδT cells exhibit tumoricidal properties, some subsets, particularly those producing IL-10, can have immunoregulatory functions that suppress anti-tumor immunity, thus limiting their therapeutic potential." (PMID 40226616, 2025). "Beyond autocrine TGF-β and IL-10, tumor cells in the microenvironment also downregulate DC surface MHC-II and CCR7 expression by secreting IL-10, IL-6, and others, thereby disrupting antigen presentation." (PMID 41346579, 2025). "Patients 117, 121, and 122 exhibited clear remodeling of their tumor microenvironments, with increased IL-2 and decreased IL-10 expression, mirroring our in vitro and murine results." (PMID 41459907, 2025). "In this study, we investigated the expression levels of IL-2, IL-10, IL-6, and TNF-α and assessed their associations with clinical and pathological tumor features." (PMID 40869161, 2025). "To analyze the neutrophil properties, we used the following frequently mentioned profiles: pro-tumor anti-inflammatory profile (Mmp9, Vegfa, Arg1, Nos2, Ccl17, Il10) and anti-tumor pro-inflammatory profile (Icam1, Tnfa)." (PMID 40001601, 2025). "IL-10 further suppresses the immune response of T lymphocytes in the tumor microenvironment while promoting EMT by reducing the activity of inhibitory factors such as miR-200." (PMID 40362280, 2025). "The mechanisms by which C5a-C5aR1 promotes tumor immune escape include: Firstly, C5a recruits myeloid-derived suppressor cells (MDSCs) to the tumor site via C5aR1, where they secrete IL-10, TGF-β, and other cytokines that suppress T cell function." (PMID 41373839, 2025). "These PD-1+ TAMs adopt an M2-like phenotype, directly engaging PD-L1–expressing tumor cells and secreting IL-10, thereby inhibiting CD8+ T cell proliferation and effector function." (PMID 41459539, 2025). "In the tumor microenvironment, Tregs can be expanded by various factors, including cytokines like IL-10 and TGF-β that are often secreted by MDSCs themselves." (PMID 41583453, 2025). "IL-10 is an immunosuppressive cytokine that inhibits antigen presentation and promotes regulatory T cell differentiation, potentially enabling tumor immune evasion." (PMID 41007766, 2025). "The Biocarta pathway results showed that cluster A is significantly associated with pathways such as tumor immune dysfunction and exclusion (TID), silencer of death domains (SODDs), IL17, IL10, and inflammation (INFLAM)." (PMID 40026531, 2025). "For instance, neutralising IL-10 with an antibody potentiated anti-tumour immune reaction in a preclinical model mimicking human CRC liver metastases." (PMID 39780187, 2025). "Tumor-associated macrophages are a primary infiltrate in the tumor microenvironment and primarily exhibit tumor- and metastasis-promoting behaviors through the secretion of elevated amounts of IL-10." (PMID 40219336, 2025). "This polarization was accompanied by elevated secretion of TGF-β and IL-10, key cytokines that contribute to the development of immunosuppressive tumor microenvironments." (PMID 41573746, 2025). "The assessment of markers associated with immune-suppressive activities in splenic granulocytes (CD11b+Ly6G+) showed elevated mRNA levels of Il10, Vegfa, Tgfb1, and Arg1 in the tumor-bearing vehicle-control group compared to naïve mice." (PMID 41282257, 2025). "TLR7 signaling can also suppress anti-tumor immune cells through cytokine production, notably IL-10." (PMID 41157253, 2025). "Because UA liposomes prevent STAT5 phosphorylation and IL-10 release, they can decrease tumor-infiltrating Tregs." (PMID 40230883, 2025). "M2-polarized TAMs drive tumor progression through immunosuppression by secreting IL-10 and TGF-β to inhibit CD8+ T cells and recruit Tregs via CCL17/CCL22." (PMID 40422244, 2025). "Elevated levels of IL-10 in the serum and surrounding tumors have been detected in multiple types of cancers, including LC, suggesting the role of IL-10 in modulating tumor-related immune responses." (PMID 41179937, 2025).
tumor (continued). "Bregs have been detected in the peripheral blood of patients with gastric cancer, where they mediate tumor immune evasion via IL-10 signaling." (PMID 41285707, 2025). "EVs suppress T cell function by delivering PD-L1, FasL, TGF-β, and IL-10, leading to T cell exhaustion and reduced anti-tumor immunity." (PMID 40574844, 2025). "IL-10−/− mice exhibited earlier onset and greater tumor incidence compared to controls, whereas IL-10TG mice were protected from tumor formation." (PMID 40149345, 2025). "M2 TAMs promote the antiapoptotic ability of tumor cells by secreting IL-6, IL-10 and other cytokines and increase the resistance of tumor cells to chemotherapy drugs." (PMID 40850976, 2025). "The dual roles of key cytokines such as TNF-α, TGF-β, IL-6, and IL-10, which act as both tumor suppressors and promoters depending on the tumor context, highlight the complexity of targeting these pathways therapeutically." (PMID 40933989, 2025). "It is generally considered to have anti-tumor properties, and their activity is suppressed by CAFs and tumor cells by secreting cytokines such as IL-8, IL-10, and TGF-β." (PMID 40427098, 2025). "Some studies have pointed out that the Th2 cells secrete IL-4 and IL-10, which promote tumor growth or metastasis by inducing immunosuppression." (PMID 39235554, 2025). "For example, studies suggest that tumor-promoting Th2 cells exhibit high levels of IL-10 and TGF-β, whereas Th2 cells with elevated expression of IL-3, IL-5, and IL-13 demonstrate anti-tumor immunity." (PMID 40070825, 2025). "In melanoma, PI3Kγ inhibition similarly disrupts the immunosuppressive TME by blocking TAM‐mediated IL‐10 production and T cell exclusion, sensitising tumours to PD‐1 blockade." (PMID 40434054, 2025). "On one hand, IL-10 can induce tumor immune escape, promote tumor progression and metastasis by inhibiting the antigen-presenting function of APCs, suppressing T cell activation and immune response, and producing inhibitory factors." (PMID 39980556, 2025). "Although IL-10 has anti-inflammatory properties that can prevent excessive tissue damage, its release in the TME is often associated with immune suppression and tumor progression." (PMID 40486614, 2025). "Th1 cells enhance antitumor immune responses by secreting interferon-γ (IFN-γ), while Th2 cells create an immunosuppressive TME by secreting IL-4 and IL-10, weakening cell-mediated immune responses and promoting tumor immune evasion." (PMID 40599775, 2025). "For example, the intense initial inflammatory activity of M1 macrophages in tumors is regulated by Th2 cells and cytokines such as IL-4 and IL-10 to achieve an effective yet controlled anti-tumor response." (PMID 41463479, 2025). "Tumor cells can upregulate PD-L1 or secrete IL-10 and TGF-β to counteract the pro-inflammatory and immune-activating effects of Th1 cells." (PMID 39930476, 2025). "Our results demonstrated that IL-6, IL-1β, and IL-10 were overexpressed in tumor tissues compared with normal mucosa." (PMID 41267807, 2025). "In contrast, M2 macrophages produce various anti-inflammatory cytokines, e.g., IL-10, IL-13, and IL-4, exerting immunosuppressive effects that favor tissue repair and tumor progression 25,26." (PMID 40365295, 2025). "This shift increases pro-inflammatory cytokines, such as IL-12, and decreases immunosuppressive cytokines like IL-10, enhancing the immune response within the tumor microenvironment." (PMID 40330466, 2025). "Meanwhile, Tregs produce suppressive cytokines such as IL-10, further inhibiting the activity of effector T cells and accelerating tumor cell invasion." (PMID 40704062, 2025). "Tumor-derived cytokines (IL-4, IL-10, TGF-β) activate STAT6 and SMAD pathways, reinforcing M2 immunosuppression." (PMID 40417220, 2025). "TAMs secrete various signaling molecules, including TGF-β, VEGF, and IL-10, which suppress the antitumor functions of effector T cells, thereby facilitating tumor cell growth." (PMID 41142826, 2025).
tumor (continued). "We measured intratumoral IL-10 levels to evaluate the impact of treatments on the tumor microenvironment." (PMID 40403026, 2025). "Components such as regulatory T cells (Tregs), myeloid-derived suppressor cells (MDSCs), tumor-associated fibroblasts (CAFs), and immunosuppressive cytokines like TGF-β and IL-10 create an inhibitory milieu that limits CAR-T efficacy." (PMID 41348261, 2025). "Under certain contexts, IL-10 can activate immune cells and directly stimulate anti-tumor responses by increasing IFN-γ secretion." (PMID 40563367, 2025). "At lower doses, IL-10 has anti-inflammatory effects, whereas higher concentrations promote the activation and proliferation of tumor-infiltrating CD8+ T cells." (PMID 40410571, 2025). "sncRNAs also contribute to the creation of an immunosuppressive microenvironment by influencing tumor cells or tumor-associated macrophages to secrete inhibitory cytokines, such as transforming growth factor-β (TGF-β) and interleukin-10 (IL-10)." (PMID 41019058, 2025). "Particularly, they directly or indirectly suppress CD8+ tumor-infiltrating lymphocytes, release immunosuppressive factors such as IL-10, and enhance tumor cell growth and extravasation by fostering vascularization and extracellular matrix (ECM) remodeling." (PMID 40670983, 2025). "IL-10 is a pleiotropic cytokine that exerts both tumor-promoting and suppressive functions and plays a critical role in immune homeostasis." (PMID 40868199, 2025). "IL-10 acts as an immunosuppressant, inhibiting T-cell and macrophage activity, which facilitates immune evasion by tumor cells and promotes tumor progression." (PMID 40004863, 2025). "Although these cells often reside in close proximity in the TME, cytokines such as TAM- and tumour-derived IL-10 still exert broad immunosuppressive effects, dampening both macrophage and NK cell effector functions." (PMID 40948757, 2025). "M2‐type TAMs, Tregs, and MDSCs promote tumor growth and immune evasion by secreting factors like IL‐10, TGF‐β, VEGF, and MMP9." (PMID 40916616, 2025). "COX-2 drives the expression of prostaglandins and creates a pro-tumour environment via the upregulation of immunosuppressive cytokines such as interleukin-10 (IL-10), and pro-inflammatory cytokines (such as IL-6)." (PMID 41463341, 2025). "GBM cells release IL-6, IL-10, and express PD-L1, fostering T regulatory and myeloid-derived suppressor cell generation, impairing anti-tumor immune responses." (PMID 40106404, 2025). "Among these cytokines, interleukin-10 (IL-10) has garnered significant interest due to its dual roles in cancer biology, exhibiting both tumor-suppressive and tumor-promoting properties." (PMID 40149345, 2025). "High molecular weight HYA also stimulates IL-10 production, thereby reducing inflammation in the tumor environment." (PMID 39857021, 2025). "This process led to increased IL-10 accumulation in the tumor microenvironment, suppressing T-cell activity." (PMID 39979245, 2025). "PPARγ activation enhances the function of anti-tumor immune cells, such as CD8 + T cells and natural killer (NK) cells, by promoting the secretion of anti-inflammatory cytokines like IL-10 and TGF-β in tumor-associated macrophages." (PMID 40926269, 2025). "In HCC, inflammation-induced IgA+ cells directly inhibit cytotoxic CD8+ T cells in the liver by expressing programmed death-ligand 1 (PD-L1) and interleukin-10 (IL-10), thereby promoting tumor progression." (PMID 41357192, 2025). "Tumor-associated M2 macrophages and CD4+ CD25+FoxP3+ regulatory T-cells (Tregs) suppress anti-tumor immune responses through secretion of immunosuppressive cytokines IL-10 and TGFβ, and presentation of CTLA4 on T cells and PD-L1 on macrophages." (PMID 40831543, 2025). "Tregs enhance tumor invasiveness through Foxp3-dependent epigenetic reprogramming, secrete IL-10 and TGF-β to inhibit CD8+ T cell cytotoxicity, and downregulate costimulatory molecules, hindering effective T cell activation." (PMID 40510347, 2025).
tumor (continued). "The immunosuppressive state is characterized by the presence of regulatory T cells (Tregs), tumor-associated macrophages (TAMs), and immunosuppressive cytokines such as TGF-β and IL-10." (PMID 40336138, 2025). "Pollutants such as cadmium and arsenic have been reported to promote the differentiation of B cells into phenotypes that secrete IL-10, thereby fostering a tumor-promoting microenvironment." (PMID 40137490, 2025). "In the tumor itself, the molecule has the ability to reduce ROS, interleukin 10 (IL-10) and nitric oxide (NO) levels." (PMID 41019086, 2025). "IL-10, secreted by tumor cells, TAMs, Tregs, and DCs, can inhibit the recruitment and activity of tumor-infiltrating T cells, upregulate the expression of PD-L1 in monocytes, and promote the aggregation of MDSCs." (PMID 41514551, 2025). "The pleiotropic role of IL-10 seems to depend on the context and the concentration, but it is currently believed that this cytokine can promote the activation of tumor-resident CD8+ T cells." (PMID 40236706, 2025). "Activated M2 macrophages secrete IL-10 to promote Th2 differentiation and PD-L1 upregulation, accelerating T-cell apoptosis and establishing a pro-tumor immunosuppressive feedback loop." (PMID 40896442, 2025). "In contrast, the M2‐like macrophage‐derived cytokines IL8 and IL10 promote the expression of ITGβ8 on tumor cells, and SPI1 mediates this effect." (PMID 39535362, 2025). "Further, IL-10 inhibits the activation of antigen-presenting cells and effector T cells, thereby impairing anti-tumor immune responses and creating an immunosuppressive TME." (PMID 40933989, 2025). "These M2 macrophages are characterized by increased TGF-β and IL-10 levels and can promote the migratory capacity of tumor cells." (PMID 40612677, 2025). "While TAMs drive tumor progression through established pathways such as CSF1‐mediated recruitment or IL‐10‐induced immunosuppression, our discovery of the SRC‐1/STAT1/MMP12 axis revealed a distinct mechanism specific to PNI." (PMID 40985319, 2025). "This research underscores the potential of IL-10-modified CAR-T cells in improving anti-tumor responses, particularly in challenging TME." (PMID 41584600, 2025). "The activation of heterodimers as tumor driver genes can stimulate the secretion of immunosuppressive cytokines such as IL‐10, helping tumors escape immune surveillance." (PMID 40727252, 2025). "For example, Tumor-associated macrophages (TAMs), attracted by tumor-derived chemokines like CCL2 and CSF-1, often adopt an M2-like phenotype, producing anti-inflammatory cytokines like IL-10 and TGF-β." (PMID 40739089, 2025). "All groups showed a significant rise in IL-10 production upon re-stimulation with tumor antigens, especially in cells from animals treated with active OpdA." (PMID 41019059, 2025). "TICs also release cytokines and factors (like TGF-β, IL-10, and CCL2) that change tumor-associated macrophages into M2 cells and attract MDSCs." (PMID 41550427, 2025). "In contrast, M2 macrophages exhibit anti-inflammatory properties, promoting tumor progression, angiogenesis, and metastasis through stimulation by Th2 cytokines, including interleukin-4 (IL-4), IL-10, and TGF-β." (PMID 41502528, 2025). "STAT3 activation can occur independently of IL-6 targeting, as it lies downstream to other cytokines including IL-10, IL-22, and IL-27, which are broadly pro-tumor in nature and found in abundance in KM-LUAD." (PMID 40356899, 2025). "In particular, hypoxic and necrotic regions of GBM secrete chemokines such as interleukin-4 (IL-4) and interleukin-10 (IL-10), driving a shift from M1 (anti-tumor) to M2 (pro-tumor) TAMs." (PMID 40585979, 2025). "Such macrophages, also secreting immunosuppressive cytokines and chemokines, including IL‐10, IL‐13, and TGF‐β, contribute to immunosuppression and tumor progression and have also been associated with poor prognosis in patients with PDAC." (PMID 40736369, 2025).